PGRMC1 (progesterone receptor membrane component 1)
Diseases named in the same sentence as PGRMC1 in open-access papers (continued):
Sharing a sentence is not in itself a finding about the gene and the disease.
glioblastoma (5 papers, 2020 to 2025). The most malignant astrocytic tumor (WHO grade IV). "Overexpression of PGRMC1 caused marked inhibition in USMB-induced radiosensitization of glioblastoma cells." (PMID 35457210, 2022). "Recent clinical studies have further validated these findings: PGRMC1 has been demonstrated as a tumor-promoting factor in glioblastoma, where it modulates tumor progression, immune microenvironment, and therapy response." (PMID 41139924, 2025). "In contrast, PGRMC1 overexpression abolished UTMD-induced blockade of autophagic degradation in IR-treated glioblastoma cells (P < 0.01)." (PMID 35152910, 2022). "UTMD enhanced the radiosensitivity of glioblastoma partially by disrupting PGRMC1-mediated autophagy." (PMID 35152910, 2022). "In general, we have uncovered a novel mechanism whereby UTMD enhanced the radiosensitivity of glioblastoma through the inactivation of PGRMC1-mediated autophagy, at least partially." (PMID 35152910, 2022). "Collectively, our data indicated that PGRMC1-mediated autophagy played a critical role in UTMD-induced radiosensitization of glioblastoma in vivo." (PMID 35152910, 2022). "While using PGRMC1 inhibitor, AG-205 resulted in reduced cell viability and an increase in cell death suggesting abolishment of PGRMC1-mediated autophagy allows USMB enhanced radiosensitivity of glioblastoma." (PMID 35457210, 2022). "Meanwhile, AG-205 or PGRMC1 siRNA pretreatment enhanced UTMD-caused disruption of autophagy, thereby promoting UTMD-caused radiosensitization of glioblastoma cells." (PMID 35152910, 2022). "Furthermore, our results supported an important role for PGRMC1 in UTMD-mediated inhibition of autophagy in IR-treated glioblastoma cells." (PMID 35152910, 2022). "Moreover, PGRMC1 overexpression abolished UTMD-caused blockade of autophagic degradation, subsequently inhibiting UTMD-induced radiosensitization of glioblastoma cells." (PMID 35152910, 2022). "Furthermore, we also found that UTMD inhibited autophagic flux and PGRMC1 expression in IR-treated glioblastoma-bearing mice." (PMID 35152910, 2022). "Our study aimed to determine the effect of PGRMC1 on glioblastoma (GBM) pathophysiology using two independent cohorts of IDH wild-type GBM patients and stable knockdown GBM models." (PMID 37887342, 2023). "Finally, compared with IR plus UTMD group, PGRMC1 overexpression significantly increased tumor size [(3.8 ± 1.1) mm2 vs. (8.0 ± 1.9) mm2, P < 0.05] and decreased survival time [(67.2 ± 2.6) d vs. (40.0 ± 1.2) d, P = 0.0026] in glioblastoma-bearing mice." (PMID 35152910, 2022). "PGRMC1 inhibitor AG-205 or PGRMC1 siRNA pretreatment enhanced UTMD-induced LC3B2 and p62 accumulation in IR-exposed glioblastoma cells, thereby promoting UTMD-mediated radiosensitization (P < 0.05)." (PMID 35152910, 2022). "Herein, we found that PGRMC1, a membrane receptor, was also involved in UTMD-induced inhibition of autophagy and radiosensitivity of glioblastoma in vitro and in vivo." (PMID 35152910, 2022). "Meanwhile, the colocalization of PGRMC1 and LC3B2 was also markedly decreased by UTMD in IR-exposed glioblastoma cells." (PMID 35152910, 2022). "In contrast, PGRMC1 overexpression abolished UTMD-induced blockage of autophagic degradation and tumor radiation response enhancement in glioblastoma." (PMID 35152910, 2022). "Accordingly, this study aimed to investigate the effect of UTMD on the radiosensitivity of glioblastoma as well as the potential involvement of PGRMC1-mediated autophagy in vitro in cultured GL261, U251 cells and in vivo in orthotopic glioblastoma-bearing mice." (PMID 35152910, 2022). "Moreover, AG-205 or PGRMC1 siRNA pretreatment notably enhanced UTMD-induced LC3B2 and p62 accumulation in IR-exposed glioblastoma cells (P < 0.05)." (PMID 35152910, 2022). "Furthermore, UTMD inhibited PGRMC1 expression and binding with LC3B2 in IR-exposed glioblastoma cells (P < 0.01)." (PMID 35152910, 2022).
glioblastoma (continued). "Additionally, AG-205 or PGRMC1 siRNA treatment notably improved UTMD-induced radiosensitization of glioblastoma cells, and PGRMC1 overexpression markedly inhibited UTMD-induced radiosensitization of glioblastoma cells (P < 0.05)." (PMID 35152910, 2022). "However, it should be noted that all our experiments were taken in mice and cells, the effect of UTMD on radiosensitivity of glioblastoma patients had not been elucidated as well as the precise mechanisms by which UTMD inhibited PGRMC1 expression and activity." (PMID 35152910, 2022).
head and neck cancer (5 papers, 2019 to 2023). A primary or metastatic malignant neoplasm affecting the head and neck. "PGRMC1 is highly expressed in various tumors including breast, head and neck cancers and even in glioma." (PMID 35152910, 2022). "The effects of ferroptosis inducers and PGRMC1 gene silencing/overexpression were tested on head and neck cancer (HNC) cell lines and mouse tumor xenograft models." (PMID 34749765, 2021). "It is convinced that the status of PGRMC1 copy number amplification and over-expression will probably influence response to head and neck cancer treatment strategy." (PMID 31970154, 2019). "Our data revealed, previously undescribed, the oncogenic and prognosis value of PGRMC1 over-expression and copy number amplification in the head and neck cancer." (PMID 31970154, 2019). "Recent studies revealed that the expression of PGRMC1 dramatically elevated in head and neck cancer." (PMID 31970154, 2019). "Interestingly, very recent studies showed that PGRMC1 promoted an iron-dependent type of cell death (ferroptosis) in head and neck cancer cells." (PMID 37887342, 2023). "Interestingly, very recent studies from You and colleagues found that PGRMC1 expression increased sensitivity of head and neck cancer cells to ferroptosis inducers both in vitro and in vivo." (PMID 37887342, 2023). "The aberrant expression of PGRMC1 at both transcript and protein levels have been reported in multiple types of cancer, including breast, ovarian, as well as head and neck cancer." (PMID 34746100, 2021). "We believed our data reveal the potential mechanisms linking PGRMC1 expression and altered metabolism pathway in tumorigenesis and metastasis of human head and neck cancers, which will contribute to the development of anti-cancer therapies that target cancer metabolism." (PMID 31970154, 2019). "We first determined the mRNA expression of PGRMC1 in head and neck cancer samples from the TCGA database and found that the transcripts of PGRMC1 were significantly higher expressed in paired HNSC samples (N = 112) compared with adjacent normal tissues (P = 0.0035) (left)." (PMID 31970154, 2019). "Interestingly, very recent studies found that ferroptosis inducers could efficiently eliminate paclitaxel-resistant head and neck cancer cells, a phenomenon that was a consequence of high PGRMC1 levels." (PMID 37887342, 2023). "In this present study, we assessed the prognostic impact of aberrant PGRMC1 expression in head and neck cancer and other cancers to identify patients who may benefit from anti-cancer therapy targeting PGRMC1 and also investigated the oncogenic mechanism of PGRMC1 over-expression in cancer cells." (PMID 31970154, 2019). "However, to our knowledge, the oncogenic role of the PGRMC1 gene in head and neck cancer has not been systematically analyzed, and additional researches are merited." (PMID 31970154, 2019).
lung adenocarcinoma (5 papers, 2015 to 2021). A carcinoma that arises from the lung and is characterized by the presence of malignant glandular epithelial cells. "Interestingly, a putative membrane‐associated progesterone steroid receptor PGRMC1 was recently proved to be able to active β‐catenin pathway in lung adenocarcinoma." (PMID 32618411, 2020).
Cognitive impairment (4 papers, 2019 to 2023). Abnormal cognition is characterized by deficits in thinking, reasoning, or remembering. "We also reported that inhibition of PGRMC1 in mice increased brain tissue loss, sensorimotor deficits, and cognitive impairments after HIE." (PMID 36794556, 2023). "The present study aimed to investigate the effects of PROG (8,16 mg kg−1) and ALLO (8,16 mg kg−1) on the reversal of cognitive deficits induced by ketamine (30 mg kg−1) via the PGRMC1 pathway in rat brains, including hippocampus and prefrontal cortex (PFC)." (PMID 33767621, 2021). "Third, the cognitive impairment induced by ketamine was reversed by PROG and ALLO add-on treatments, and the PGRMC1/EGFR/GLP-1R/PI3K/Akt pathway was upregulated." (PMID 33767621, 2021).
endometrial cancer (4 papers, 2020 to 2025). Primary or metastatic malignant neoplasm involving the endometrium (mucous membrane that lines the endometrial cavity). "The actions of PGRMC2 are consistent with prior studies in which PGRMC1 knockdown in endometrial cancer cells dramatically reduced xenograft tumor growth in immunocompromised mice while also elevating chemosensitivity." (PMID 40227710, 2025). "PGRMC1 is increased in ovarian and endometrial cancers, and this increase contributes to tumor progression." (PMID 39194522, 2024). "As with many different types of cancers, PGRMC1 expression is elevated in ovarian and endometrial cancers." (PMID 34885064, 2021). "Xenograft studies using human ovarian and endometrial cancer cell lines in immunocompromised mice demonstrate that reduced expression of PGRMC1 results in tumors that grow substantially slower." (PMID 34885064, 2021). "The previous studies have demonstrated that PGRMC1 is highly expressed in ovarian and endometrial cancers and that its expression is regulated by both hormonal and environmental factors." (PMID 34885064, 2021). "The expression of PGRMC1 is significantly increased in both ovarian and endometrial cancers, similar to that reported in other cancer types." (PMID 34885064, 2021). "Collectively, these studies illustrate the growth-promoting and cell stress protective functions of PGRMC1 in endometrial cancer cells." (PMID 34885064, 2021). "Although focusing on ovarian and endometrial cancer, we will also present data obtained from normal ovarian and uterine cells as well as cell lines in order to provide more detailed information related to the mechanisms of action of PGRMC1 and PGRMC2." (PMID 34885064, 2021). "Interestingly, the epithelial cells of the endometrial cancer samples express elevated levels of both PGRMC1 and PGRMC2 in a manner that more closely mimics that of samples obtained from the proliferative phase of the menstrual cycle." (PMID 34885064, 2021). "This must be demonstrated by further experimentation but the findings that 1) there is an inverse relationship between the expression of PGRMC1 and PGR and 2) PGRMC1 levels increase while PGR levels decrease with the increasing grade of endometrial cancers support this concept." (PMID 34885064, 2021). "The objective of this review is to provide an overview of what is known about the roles that PGRMC1 and PGRMC2 play in ovarian and endometrial cancers, particularly as related to the mechanisms through which they regulate mitosis, apoptosis, chemoresistance, and cell migration." (PMID 34885064, 2021). "Whether this PGRMC1/PGRMC2-dependent pathway functions to regulate the proliferation of ovarian and endometrial cancer cells remains to be determined." (PMID 34885064, 2021). "Aside from one study suggesting that PGRMC1 expression increases with endometrial tumor grade and that PGRMC1 may be directly repressed by miRNA-98 in cancer cell lines, very little is known about a role for PGRMC proteins in the development and progression of endometrial cancer." (PMID 34885064, 2021).
glioma (4 papers, 2016 to 2022). A benign or malignant brain and spinal cord tumor that arises from glial cells (astrocytes, oligodendrocytes, ependymal cells). "Progesterone receptor membrane component 1 (PGRMC1) is a member of the membrane-associated progesterone receptor family that anchors to the cell membrane through the N-terminal transmembrane helix, and has been found to be highly expressed in multiple types of tumors, including glioma." (PMID 35152910, 2022). "Su and colleagues also demonstrated that PGRMC1 mediated the progesterone-induced release of neurotrophic BDNF in rat C6 glioma cells via activation of the ERK5 signaling pathway." (PMID 36266625, 2022). "Among the significantly downregulated genes, we focused on the gene encoding progesterone receptor membrane component-1 (PGRMC1) and observed that IAV H5N6 infection clearly inhibited PGRMC1 in both neuroblastoma and glioma cells." (PMID 34585989, 2021). "Therefore, the close interaction of progesterone mediated effects and PGRMC1 expression, especially in glia cells, is supposed to be a potential target to study the nPGR-independent effects of progesterone on glioma cells and, thereby, PGRMC1 was selected as protein of interest in the present study." (PMID 27340667, 2016). "Double immunofluorescent detection of PGRMC1 and PAIRBP1 identified the two proteins to be colocalized in the cells of the spheroids of both glioma cell lines." (PMID 27340667, 2016). "Therefore, the aim of the study was to investigate the effects of different concentrations of progesterone on PGRMC1, PAIRBP1, and PAQR7 expression in glioma cell spheroids on mRNA and protein levels." (PMID 27340667, 2016).
renal carcinoma (4 papers, 2017 to 2023). A carcinoma arising from the epithelium of the renal parenchyma or the renal pelvis. "Furthermore, high protein levels of PGRMC1 significantly associate with the shorter survival of renal carcinoma patients." (PMID 37887342, 2023). "Specifically, PGRMC1 is overexpressed in tumours compared to healthy tissues and associates with the poor outcome of patients with breast, head and neck, hepatocellular, or renal cancer." (PMID 37887342, 2023). "By implementing it coupled with the tissue immunohistochemical validation on a large scale, we identified the concentration of PGRMC1 is greatly increased in most of renal cancer tissues when compared with normal kidney tissues." (PMID 28107520, 2017). "Moreover an exogenous elevated abundance of PGRMC1 by plasmid transfections significantly enhanced cell proliferation of renal cancer cells in vitro." (PMID 28107520, 2017). "Sulfatide synthesis in the human renal cancer cell line SMKT-R3 was strongly inhibited in the presence of low μM concentrations of AG-205, a progesterone receptor membrane component 1 (PGRMC1) antagonist." (PMID 34944026, 2021). "Our results suggest that PGRMC1 is a novel biomarker and therapeutic target for RCC since its up-regulation promotes renal cancer cell proliferation and predicts tumor malignancy in vivo." (PMID 28107520, 2017). "Although we demonstrated that a high abundance of PGRMC1 could promote renal cancer cell growth, it is not clear PGRMC1-mediated molecular signaling pathways in carcinogenesis and cancer progression." (PMID 28107520, 2017). "However, the roles of PGRMC1 in renal cancer are not clear and merit further study." (PMID 28107520, 2017).
cervical cancer (3 papers, 2021 to 2025). A primary or metastatic malignant neoplasm involving the cervix. "Given that PGRMC1 can influence the function of cervical cancer cells at the cellular level, we conducted a mass spectrometry analysis to screen a total of 246 proteins associated with PGRMC1." (PMID 41153737, 2025). "To further validate the expression of PGRMC1 in cervical cancer, we gathered specimens from the residual portions of cervical biopsies obtained from HPV-positive patients." (PMID 41153737, 2025). "Collectively, these findings suggest that suppressing PGRMC1 expression influences the migratory capacity of cervical cancer cells." (PMID 41153737, 2025). "Patients were categorized into two groups according to the mean expression level of PGRMC1 in cervical cancer tissue microarrays: a high-expression group (expression above the mean) and a low-expression group (expression below the mean)." (PMID 41153737, 2025). "Our study expands the understanding of PGRMC1’s role in cervical carcinogenesis and provides an experimental basis for targeted therapy of cervical cancer." (PMID 41153737, 2025). "In this study, we intended to collect clinical tissue samples and utilize a cervical cancer cell line (HeLa) in vivo and in vitro to study the expression of PGRMC1 in cervical squamous intraepithelial lesion and its possible mechanism." (PMID 41153737, 2025). "Our analysis revealed that PGRMC1 expression was generally lower in cervical cancer tissues compared to normal and cervical tissues." (PMID 41153737, 2025). "To study the effect of PGRMC1 on cervical cancer, we transfected HeLa cells with siRNA to knock down PGRMC1 so as to verify its effect on the biological function." (PMID 41153737, 2025). "The positive rate of PGRMC1 protein expression in cervical tissues of different pathologic types was analyzed by using LinkedOmics database to search for the co-expressed genes of PGRMC1 in cervical cancer." (PMID 41153737, 2025). "Knockdown of PGRMC1 resulted in the inhibition of migration and invasion capabilities in cervical cancer cells." (PMID 41153737, 2025). "To explore the functional role of PGRMC1, we manipulated its expression in the cervical cancer cell line HeLa using siRNA." (PMID 41153737, 2025). "In vitro studies of uterine sarcoma and cervical cancers have demonstrated PGRMC1 to enhance the epithelial mesenchymal transition phenotypes, promote chemoresistance, and have a possible role in progression of metastasis." (PMID 34789240, 2021). "However, the role of PGRMC1 in the development and progression of cervical cancer, especially cervical intraepithelial neoplasia (CIN), has not been fully investigated." (PMID 41153737, 2025). "Consequently, our findings indicate that PGRMC1 exerts a promotional effect on cervical intraepithelial neoplasia, establishing it as a significant poor prognostic factor for cervical cancer due to its role in facilitating tumor migration and invasion." (PMID 41153737, 2025). "GO and KEGG enrichment analyses of the co-expressed genes showed that they were mainly enriched in the processes of cell adhesion and actin fiber bundle assembly, suggesting that PGRMC1 may be involved in the regulation of cell transduction pathway in cervical cancer." (PMID 41153737, 2025).
Infertility (3 papers, 2013 to 2024). "In contrast PGRMC1 over expression is associated with impaired follicular development in women undergoing gonadotropin-induced ovulation and in vitro fertilization as part of their infertility treatment." (PMID 23781168, 2013). "In infertile patients, the elevated levels of PGRMC1 were detected within ovarian (granulosa/luteal) cells harvested at the time of oocyte (egg) retrieval." (PMID 23781168, 2013). "Thereby, the results of our in vitro model explained how PGRMC1 dysregulation during decidualization may present a new perspective on infertility-related diseases." (PMID 38308254, 2024). "Taken together, we explained how dysregulated PGRMC1 expression could impact endometrial stromal cell decidualization, which may provide a new perspective on infertility-related diseases." (PMID 38308254, 2024). "Pgrmc1 expression has been correlated with tumor growth, angiogenesis, and infertility." (PMID 36009286, 2022).
Insulin resistance (3 papers, 2021 to 2025). Increased resistance towards insulin, that is, diminished effectiveness of insulin in reducing blood glucose levels. "Although fatty livers are typically associated with insulin resistance, the metabolic benefit conferred by skeletal Pgrmc1 loss outweighed the potential disadvantage from hepatic Pgrmc1 loss, thereby ameliorating systemic insulin resistance in T2D PKO mice." (PMID 41208560, 2025). "A recent translational study demonstrated decreased levels of PGRMC1 protein and RNA in patients with insulin resistance, suggesting a role of PGRMC1 in insulin signaling." (PMID 34970218, 2021).